CD4 (CD4 molecule)
Diseases named in the same sentence as CD4 in open-access papers (continued):
Sharing a sentence is not in itself a finding about the gene and the disease.
AIDS (continued). "Among 400 participants whose CD4 cell count was available, the AIDS-free proportion decreased rapidly each year where the CD4 cell count was less than 200 cells/μL." (PMID 16710078, 2006). "Very low CD4+ cell percentages consistent with a laboratory diagnosis of AIDS have rarely been described in HIV-uninfected children with or without mixed infections." (PMID 17042940, 2006). "The hazard ratio for progression to AIDS or death before 1997 was 50.8 in CD4 cell counts of less than 200 cells/μL compared with those of 500 cells/μL or more." (PMID 16710078, 2006). "The effect of the CD4 cell count as a predictor of progression to AIDS or death before and after HAART usage was evaluated." (PMID 16710078, 2006). "HBV infection has been associated with more rapid progression to AIDS, explained by an increased expression of HIV-infected cells and faster decrease in CD4 lymphocytes." (PMID 16600028, 2006). "Risk factors significantly associated to failure of vaccination in previously reports, were the degree of immunosuppression and clinical markers of advanced HIV disease like CD4 count at vaccination and history of an AIDS-defining event." (PMID 16600028, 2006). "Trends in standardized incidence ratios (SIRs) were assessed by CD4 count, AIDS-relative time, and calendar time." (PMID 16868538, 2006). "It is not rare for patients, such as those followed in the present study, to first receive HAART after they develop an AIDS event or their CD4 cell count falls below 200/mm3." (PMID 16262894, 2005). "The NYC resident meets one criterion for the diagnosis of AIDS; his CD4+ T-cell count is less than 200 cells/mm3." (PMID 15743534, 2005). "The median CD4 count at which the initial AIDS-defining condition occurred was 27 (inter-quartile range 11 – 63)." (PMID 15538953, 2004). "D-dimer is an endothelial biomarker of inflammation and coagulation, and it has been shown to be associated with serious non-AIDS events (cardiovascular disease, cancer, serious renal and hepatic disease) and mortality in virally suppressed people with HIV with moderate to high CD4+ cell counts." (PMID 40971458, 2026). "This review underscores the significance of CD4/CD8 ratios as not only diagnostic indicators but also as potential targets for therapeutic intervention, heralding new horizons in the battle against HIV/AIDS." (PMID 41630206, 2026). "This increased risk of viral non‐suppression after resuming ART, combined with other adverse outcomes such as slower CD4+ cell count increases, faster progression to AIDS and increased mortality, indicates a need for further interventions designed to retain people on ART." (PMID 41555785, 2026). "Regarding clinical variables, the authors found that regardless of the tool used, patients with AIDS, opportunistic infections, and low CD4 T-cell count (≤ 200 cells/mm3) had higher sarcopenia risk scores." (PMID 39752996, 2025). "Transthoracic echocardiography (TTE) is an invaluable tool for the early detection of cardiac dysfunction in asymptomatic HIV-positive individuals and acquired immunodeficiency syndrome (AIDS) patients, especially in patients with advanced disease as evidenced by low CD4+ counts." (PMID 41019440, 2025). "In this study, 7 key variables, including hemoglobin, age at HAART treatment, infection route, WBC count, education level, BG, and CD4 count before HAART, were identified as critical factors predicting all-cause mortality after HAART in people living with HIV and AIDS." (PMID 40456121, 2025). "The previously known factors associated with immune nonresponse, such as a history of AIDS, a low CD4 nadir, and a low CD4/CD8 ratio, were also observed in our study as expected." (PMID 39868926, 2025). "We then also excluded diagnoses with unknown CD4+ T cell count or AIDS status (n = 8,426), and, due to small numbers, transgender cases and cases of unknown sex (n = 358), resulting in 28,521 cases included in our analyses." (PMID 41311323, 2025).
AIDS (continued). "KIR2DS2 is associated with a more rapid decline in CD4+ T lymphocytes and progression to AIDS without affecting viral load." (PMID 40244151, 2025). "For natural deaths, we used the CD4 count at death as a proxy for AIDS‐related mortality." (PMID 40826829, 2025). "The patient was diagnosed with HIV/AIDS with a CD4+ count of 154 cells per cubic millimeter and a positive rapid plasma reagin test (titer 1:128), with cerebrospinal fluid demonstrating elevated white blood cell count and protein concentration, consistent with neurosyphilis." (PMID 39903617, 2025). "Moreover, the high incidence of AIDs in women correlates well with different effects of CD25+CD4+Foxp3+Tregs and CD8+Tregs in immunoregulation in both sexes." (PMID 41009359, 2025). "Lower CD4 counts (<200) in AIDS patients increase the likelihood of both PTB and EPTB." (PMID 40748951, 2025). "Chronic HIV infection leads to the progressive depletion of CD4+ T cells and functional exhaustion of CD8+ T cells, ultimately resulting in acquired immunodeficiency syndrome (AIDS) (1, –, 3)." (PMID 41277843, 2025). "Therefore, we tested Clec7a−/−Fcer1g−/− compared with Card9−/− and wild-type (WT) mice in the mouse CD4-deficient PCP model, which mimics CD4 impairment during AIDS." (PMID 39745390, 2025). "Interestingly, we found that the number of patients with CD4 counts below 200/μL, which should be considered confirmatory for AIDS, consistently exceeded the rate of AIDS onset diagnoses each year." (PMID 39869625, 2025). "The CD4/CD8 ratio has thus been associated with a spectrum of comorbidities, including cerebrovascular conditions, neurocognitive disorders, chronic kidney and obstructive pulmonary diseases and non-AIDS malignancies." (PMID 40303366, 2025). "In addition, the measurement of CD4 cell counts is a strong predictor of progression to AIDS and a means of monitoring ART." (PMID 40260411, 2025). "Thus, Nef and Vpu contribute to the pathogenicity of HIV-1, CD4+ T cell depletion, and progression to AIDS." (PMID 40911682, 2025). "CrAg lateral flow assay is approved for patient management in India, but the National AIDS Control program may consider access at all ART centers for reflexive screening of all PLHIV with CD4 count < 100 cells / mm3." (PMID 40275253, 2025). "Consequently, there is a paucity of data on the long-term trends in CD4+ T-cell counts among patients with HIV/AIDS receiving CM therapeutics." (PMID 41262939, 2025). "HIV-1 is the virus responsible for acquired immunodeficiency syndrome (AIDS), which is characterized by an attack and disruption of CD4+T cells, with the consequence of significant vulnerability in humans against different types of infection." (PMID 41009589, 2025). "Late presentation was defined as CD4 < 350 cells/μL or the presence of AIDS-defining conditions." (PMID 40950964, 2025). "A CD4+ T-cell count of 350 cells/μL is a critical threshold in AIDS-related research." (PMID 40027893, 2025). "Human Immunodeficiency Virus/Acquired Immunodeficiency Syndrome (HIV/AIDS) is a chronic condition characterized by compromised immune function, resulting in a progressive decline in Cluster of Differentiation 4 (CD4) cell count and an increase in viral load." (PMID 40406087, 2025). "The higher mortality rate in this study may relate to the clinical profile of participants; specifically, 20% had advanced HIV/AIDS with severe immunodeficiency, as indicated by low CD4 counts, at the time of ART initiation." (PMID 40055762, 2025). "Moreover, killer immunoglobulin-like receptor (KIR)-positive CD8+T cells target self-reactive helper CD4+T cells to protect against AIDs, such as celiac disease and multiple sclerosis (MS)." (PMID 41009359, 2025). "Only 42% had CD4 ≥ 350 cells/mm3 and 20% had AIDS-defining conditions." (PMID 41472237, 2025). "Low CD4 counts, permanently loss to care and treatment at non-capital city were significantly associated with higher AIDS-related mortality." (PMID 40330708, 2025).
AIDS (continued). "We describe regional trends over time in measurement of CD4 count at first ART initiation among 1.35 million adult PWH in 42 countries at treatment programs within the global International epidemiology Databases to Evaluate AIDS (IeDEA) collaboration." (PMID 39501773, 2025). "Furthermore, it induced durable protective immunity against gp120-expressing B16 melanoma tumors in mice, providing a new pathway for AIDS patients with DC dysfunction and CD4 T cell deletion." (PMID 41050925, 2025). "In patients with chronic HIV-1 infection or late-stage AIDS, reduced CD4 availability may lead to decreased target-mediated clearance of Nb457-NbHSA-Nb457." (PMID 40970711, 2025). "Moreover, in line with evidence of an interplay between PML and HIV persistence, solubilized realgar can disrupt HIV latency, the main barrier to an HIV/AIDS cure, in CD4 T cells of people living with HIV." (PMID 40271739, 2025). "The modulation of cellular pathways of programmed cell death has proved to be a promising approach in the conservation of the immune function in HIV/AIDS, as it prevents the depletion of CD4+ T lymphocytes as well as the chronic inflammatory process associated." (PMID 41463453, 2025). "In a humanized mouse model of infection, HIV-1 protease cleavage of CARD8 in CD4+ T-cells results in caspase-1 inflammasome assembly and pyroptosis, leading to depletion of these cells, which is one of the hallmarks of disease progression in AIDS." (PMID 39883598, 2025). "The patient had a medical history significant for HIV/AIDS with a nadir CD4 count of 5 cells/μL, diabetes mellitus type 2, asthma, hyperlipidemia, anxiety, depression, iron deficiency anemia, cervical intraepithelial neoplasia, chronic adenoid hypertrophy, and seizure disorder." (PMID 41246707, 2025). "A higher rate of VTE was observed in HIV-infected patients younger than 50 years of age (3.31% versus 0.53% in age-matched healthy controls, p < 0.0001), with a CD4+ cell count less than 200 cells/mm3 or with a diagnosis of acquired immunodeficiency syndrome (AIDS)." (PMID 40872326, 2025). "It was concluded that an early initiation of ART showed a significant reduction in the risk of developing AIDS and serious non-AIDS events compared to deferring treatment until CD4 counts fell below 350 cells/μL." (PMID 39940695, 2025). "In immunocompromised individuals, particularly those with HIV/AIDS (Acquired Immunodeficiency Syndrome), impaired CD4+ T-cell responses hinder the development of protective immunity, increasing susceptibility to disseminated cryptococcosis and meningoencephalitis." (PMID 40985415, 2025). "In patients with GB and mice with GB, the number of CD4 T lymphocytes in the blood (systemic lymphopenia) in some cases may correspond to the number of CD4 T lymphocytes in AIDS." (PMID 41426972, 2025). "Incomplete CD4+ T cell recovery is associated with an increased risk of non-AIDS-related complications, including cardiovascular disease and neurocognitive disorders." (PMID 40184131, 2025). "In this study, the reduced number of CD4 cells in patients with AIDS may have led to the attenuation of cell-mediated immunity by Th1 cells." (PMID 40356617, 2025). "HIV, a retrovirus responsible for acquired immunodeficiency syndrome (AIDS), primarily targets CD4+ T cells." (PMID 40899610, 2025). "In advanced stages, once acquired immunodeficiency syndrome (AIDS) is established, granuloma formation is severely impaired due to poor cellular recruitment, low CD4+ T-cell counts, and a high bacillary load of acid-fast bacilli." (PMID 41304139, 2025). "AIDS, in turn, is the result of a progressive drop in the CD4+ TL count, resulting from a severe state of immunodeficiency, especially when the number of CD4+ TL falls below 200 cells/mm3, weakening the individual and favoring opportunistic infections and even the development of neoplasias." (PMID 40867808, 2025). "The AIDS stage was identified in 60% cases, with a nadir of CD4 below 200/mm3 in 54% of patients." (PMID 40870513, 2025).
AIDS (continued). "In univariate analysis, prior AIDS-related events were associated with a lower probability of new HPV infections (hazard ratio, HR 0.40, 95% CI 0.17–0.95, p = 0.037), while a CD4 count > 500 cells/mm3 was associated with a higher probability (HR 1.89, 95% CI 1.03–3.47, p = 0.041)." (PMID 39857082, 2025). "Non-adherence can lead to an increase in viral load, lower CD4 cell counts, and higher mortality from PLwHIV, as the infection worsens and diseases associated with acquired immunodeficiency syndrome (AIDS) develop." (PMID 40560021, 2025). "Nonetheless, although a lower normalization rate, it should be noted that in most individuals from our two study groups, the CD4+/CD8+ T cell ratio was greater than 0.5, and values above these levels have been associated with a decreased risk of non-AIDS–related events." (PMID 40969513, 2025). "The CAR, extrapulmonary disseminated tuberculosis, other pulmonary infectious diseases, and pulmonary cavitation resulted in an increased risk of treatment failure in patients with AIDS combined with PTB, whereas an increase in the CD4+ T-cell counts reduced the risk of treatment failure." (PMID 40510348, 2025). "However, the number of AIDS cases recorded from the survey was closer to the number of people with CD4 counts below 200/μL." (PMID 39869625, 2025). "Furthermore, viral loads were higher and CD4+ T cell counts were lower in AIDS/VL versus asymptomatic coinfection groups." (PMID 40096173, 2025). "Additionally, HIV/AIDS-related tests such as CD4 counts, liver function tests, renal function tests, hematologic tests, and cervical cancer screening were available." (PMID 40589828, 2025). "Human immunodeficiency virus (HIV) is a retrovirus from the Retroviridae family responsible for acquired immunodeficiency syndrome (AIDS), characterized by the severe depletion of CD4+ T lymphocytes." (PMID 40733502, 2025). "In epidemiologic studies, a poor immune reconstitution profile (e.g., CD4+ count remaining <350–500/μL or CD4+/CD8+ ratio < 0.5) correlates with higher all-cause mortality and serious non-AIDS events, reflecting the lasting impact of immune deficiency and inflammation on overall health." (PMID 40868140, 2025). "Therefore, the diagnosis of clinically significant NTM disease itself strongly suggests that the underlying immunosuppressive state is already profound, potentially reaching advanced AIDS levels (typically characterised by very low CD4+ T cell counts)." (PMID 40936199, 2025). "Disseminated NTM (DNTM) is a rare and refractory infection with no definitive curative therapeutic options that mostly occurs in patients with impaired immunity, especially human immunodeficiency virus/acquired immunodeficiency syndrome (HIV/AIDS) patients with decreased CD4+ cell counts." (PMID 39898691, 2025). "Both treatment cohorts’ mean CD4 count increased at their last AIDS Clinics visit." (PMID 40460167, 2025). "It contrasts with earlier observations that linked M. bovis disease to advanced AIDS—for example, a study in California reported that HIV patients with M. bovis TB were usually severely immunosuppressed (CD4 ≤ 200 cells/μL) and frequently had abdominal involvement." (PMID 40700328, 2025). "Individuals who developed NADCs were older, more frequently reported a history of heterosexual transmission, had a higher rate of smoking, lower nadir and baseline CD4+ T cell counts, and a higher frequency of prior AIDS diagnoses, as well as HCV and HBV coinfections." (PMID 41194922, 2025). "A 12‐week oral course of (neem leaf) extract acetone water (IRAB) in HIV/AIDS patients significantly affected CD4 cells (which HIV decreases) in vivo without causing any adverse side effects." (PMID 40901661, 2025). "Accordingly, the CD4 T-lymphocyte percentage was much lower in PWH with AIDS in our study." (PMID 39067055, 2025). "Patients with CD4 count ≥ 500 cells/mm3 at baseline had lower AIDS-related mortality." (PMID 39058196, 2024).
AIDS (continued). "The number of circulating CD4+ T cells in PLWH predicts the onset of overt immunodeficiency and acquired immunodeficiency syndrome (AIDS)." (PMID 39057767, 2024). "However, over half of the people newly diagnosed with HIV in Europe are late-presenters with clear cellular immunodeficiency (CD4 + T-cell count below 350 cells/mm3), often complicated by an acquired immunodeficiency syndrome (AIDS)." (PMID 39731054, 2024). "Patients with Human Immunodeficiency Virus/Acquired Immunodeficiency Syndrome (HIV/AIDS) and a low CD4 count have decreased humoral and cellular immunity, predisposing them to opportunistic infections." (PMID 39221366, 2024). "Regarding HIV-related characteristics, all people with HIV has been receiving antiretroviral treatment for a median (IQR) of 7.22 (3.86–13.2) years, 46 of 451 (10.2%) had a previous AIDS event, and the median CD4+ lymphocyte nadir (IQR) was 346/μL (228–492/μL)." (PMID 39498171, 2024). "Acquired immunodeficiency syndrome (AIDS) is the final stage of the infection caused by human immunodeficiency virus type 1 (HIV-1), the agent responsible for compromising the immune system through the destruction of CD4+ T lymphocytes." (PMID 38932341, 2024). "The patient was diagnosed with AIDS due to her CD4 count<200 and AIDS-defining illness." (PMID 39398847, 2024). "EcoHIV establishes persistent infection in mice but does not cause AIDS as described in humans, as these animals maintain CD4 + T cell/CD8 + T cell ratios even after several months post-infection." (PMID 39609320, 2024). "In individuals with advanced HIV/AIDS and CD4+ T cell counts below 200 cells/ul, in addition to P. jirovecii, other opportunistic infections (such as Mycobacterium, Cryptococcus, Aspergillus and Penicillium marneffei) as well as mixed infections were also significantly increased at risk." (PMID 39372273, 2024). "The clinical expert group of the Henan Provincial Traditional Chinese Medicine AIDS Treatment emphasizes that intervention with Yi Ai Kang capsules in patients with HIV can stabilize or slow the decline in CD4+ T lymphocytes, reduce viral loads, enhance quality of life, and extend survival." (PMID 39175814, 2024). "Long-term latency of CD4 + T cells poses a significant challenge in the eradication of AIDS." (PMID 38433280, 2024). "Immune Reconstitution inflammatory syndrome (IRIS) is observed in patients who have a diagnosis of AIDS with opportunistic infections in the setting of Acquired Immunodeficiency Syndrome (AIDS) with recovering CD4+ T cell counts on Highly Active Antiretroviral Therapy (HAART)." (PMID 38594487, 2024). "Moreover, the NK cell count was highly sensitive in indicating AIDS stage defined as a CD4+ count < 200 cells/mm3, while B cells showed a low sensitivity." (PMID 38398466, 2024). "All patients had low CD4+ count, a pervasive observation in relapsing VL with AIDS." (PMID 38491526, 2024). "AIDS is defined by a cluster of differentiation four (CD4) count of less than 200 cells/mm3." (PMID 39439637, 2024). "Growth hormone therapy has been shown to have a major role in thymopoiesis when used over longer periods, as suggested by its use in immune reconstitution in patients with AIDS that show a marked increase in thymic mass and numbers of naïve CD4+ T cells after six months of GH therapy." (PMID 38566781, 2024). "Lower mean lymphocyte CD4+ count is the primary marker of VL relapse among AIDS patients." (PMID 38921748, 2024). "Thus, CD4 has ever since been widely used as a strong prognostic factor and a criterial term for the definition of the AIDS stage." (PMID 38398466, 2024). "It was previously documented that CD4 count correlated with oral manifestations of AIDS." (PMID 38373939, 2024). "Patients with HIV may present with CD4 counts below 200 cells/mm3, indicating a diagnosis of acquired immunodeficiency syndrome (AIDS)." (PMID 39807457, 2024).